DCTD (dCMP deaminase)
Description:
Catalyzes the deamination of dCMP to dUMP, providing the nucleoside monophosphate substrate for the thymidylate synthase/TYMS. Also, part of a nucleotide salvage pathway that eliminates epigenetically modified 5-hydroxymethyl-dCMP (hmdCMP) in a two-step process entailing deamination to cytotoxic 5-hydroxymethyl-dUMP (hmdUMP), followed by its hydrolysis into 5-hydroxymethyluracil (hmU) and 2-deoxy-D-ribose 5-phosphate (deoxyribosephosphate). Catalyzes the first step in that pathway, the deamination of 5-hydroxymethyl-dCMP (hmdCMP).
Tractability: Small molecule: a high-quality ligand is known; it has a binding pocket of medium quality. PROTAC: ubiquitination databases record sites on it; its protein half-life has been measured.
Target class: Enzyme; Hydrolase
Gene: Protein-coding gene on chromosome 4 (182,890,060 to 182,917,936, reverse strand). Ensembl gene ENSG00000129187.
Subcellular location (Human Protein Atlas): Cytosol; Nucleoplasm
Pathways (Reactome):
Metabolism: Interconversion of nucleotide di- and triphosphates
Gene Ontology:
Molecular function: 5-hydroxymethyl-dUMP N-hydrolase activity; identical protein binding; protein binding; dCMP deaminase activity; hydrolase activity; zinc ion binding
Biological process: nucleoside salvage; dTMP biosynthetic process; dUMP biosynthetic process; pyrimidine nucleotide metabolic process
Cellular component: cytosol
Genetic constraint (gnomAD): Loss-of-function variants: 15 observed, 10.02 expected, observed/expected ratio (o/e) 1.5, 90% interval 0.98 to 1.92. The upper end of that interval is the gene's LOEUF score, 1.92, which puts it in group 6 of 6, group 1 being the genes least tolerant of losing a copy. Missense variants: 146 observed, 156.28 expected, observed/expected ratio (o/e) 0.93, 90% interval 0.82 to 1.07. Synonymous variants: 47 observed, 59.93 expected, observed/expected ratio (o/e) 0.78, 90% interval 0.62 to 1.
Homologues: Orthologues: chimpanzee DCTD (100% identical), macaque DCTD (98% identical), guinea pig DCTD (95% identical), rabbit DCTD (93% identical), mouse Dctd (93% identical), rat Dctd (93% identical), dog DCTD (91% identical), pig DCTD (81% identical), tropical clawed frog dctd (80% identical), zebrafish dctd (78% identical), Drosophila melanogaster CG6951 (49% identical), Caenorhabditis elegans ZK643.2 (34% identical). Paralogues in human: CDADC1 (29% identical).
Diseases named in the same sentence as DCTD in open-access papers:
DCTD is named in the same sentence as 11 diseases in open-access papers, as found by Europe PMC text mining. Sharing a sentence is not in itself a finding about the gene and the disease. The quoted sentences say what the papers report.
glioma (2 papers, 2017 to 2025). A benign or malignant brain and spinal cord tumor that arises from glial cells (astrocytes, oligodendrocytes, ependymal cells). "The present study indicates a potential role for DCTD in the invasion capacity of glioma cells and our observations warrants further studies." (PMID 28912488, 2017). "In the present study, we proposed DCTD as a critically important gene in glioma origin and malignant progression." (PMID 28912488, 2017). "The intensive expression of DCTD in glioma patients with poorer survival suggests oncogenic features of this gene." (PMID 28912488, 2017). "To further depict the oncogenic features of DCTD, we obtained an overview of the correlations between DCTD expression level and the genomic or transcriptional alterations contributing to the origin or progression of glioma." (PMID 28912488, 2017). "This is the first report elaborating the pathological and biological role of DCTD in glioma." (PMID 28912488, 2017). "To further understand whether DCTD plays a role in malignant progression of glioma, we compared the expression levels of DCTD in different WHO grades glioma derived from four datasets." (PMID 28912488, 2017). "The IHC findings confirmed the increased expression of AEBP1, DCTD, DEPP1, DUSP6, FKBP9, and UGCG with the up‐regulation of glioma grades." (PMID 40052358, 2025).
leukemia (2 papers, 2019 to 2023). A malignant (clonal) hematologic disorder, involving hematopoietic stem cells and characterized by the presence of primitive or atypical myeloid or lymphoid cells in the bone marrow and the blood. "Taken together, these results suggest that DCTD plays a preeminent role in the metabolic activation of 5hmdC in human leukemia, and that high DCK expression can be utilized as a potential biomarker for therapeutic use of 5hmdC in human leukemia." (PMID 37378658, 2023). "Various studies have demonstrated a significant role of DCTD in metabolism of the monophosphate metabolite of the nucleoside analogs in human leukemia cells." (PMID 31022985, 2019). "This is in line with our observation that 5hmdC, the preferred substrate of DCTD, but not 5fdC, specifically inhibits colony formation in leukemia patient-derived bone marrow cells with high DCK expression." (PMID 37378658, 2023).
pancreatic cancer (2 papers, 2018). "To the best of our knowledge, we are the first group to publish data on DCTD protein expression in pancreatic cancer specimens." (PMID 29523831, 2018).
glioblastoma (1 paper, 2025). The most malignant astrocytic tumor (WHO grade IV). "There are potentially three deaminases that might account for the deamination of 5HmdC in glioblastoma: deoxycytidine deaminase, dCDA, cytidine deaminase, CDA and dCMP deaminase, DCTD." (PMID 40807411, 2025).
malignant glioma (1 paper, 2017). A grade III or grade IV glioma arising from the central nervous system. "As DCTD inhibitor gemcitabine has been proposed as an adjuvant therapy for malignant glioma, our finding also suggests a therapeutic value of gemcitabine for the patients with high expression level of DCTD." (PMID 28912488, 2017). "Since gemcitabine is a ready-made inhibitor of DCTD, we proposed a hypothesis to support the recommission of gemcitabine as an adjuvant therapy for malignant glioma with high DCTD expression." (PMID 28912488, 2017). "The gene coding a key enzyme in genetic material synthesis, dCMP deaminase (DCTD), was found to be significantly correlated with overall survival and high level of DCTD mRNA indicated shorter survival of the patients with malignant glioma in different databases." (PMID 28912488, 2017). "Additionally to our proposal that DCTD transcriptional level could have an impact on survival rate for patients with malignant glioma, our findings reveal the potential value of DCTD as a therapeutic target as well." (PMID 28912488, 2017).
pancreatic adenocarcinoma (1 paper, 2018). "Deoxycytidylate deaminase (DCTD) and ribonucleotide reductase subunit M1 (RRM1) are potential prognostic and predictive biomarkers for pyrimidine-based chemotherapy in pancreatic adenocarcinoma." (PMID 29523831, 2018).
tumor (9 papers, 2017 to 2025). "According to the GEPIA database, DCTD is ubiquitously expressed across various tissues while DCK is upregulated in at least 11 tumor types." (PMID 37378658, 2023). "To evaluate the anti-tumor effect of 5hmdC, we established a subcutaneous xenograft model using wild type and DCTD knockout Raji lymphoma cells in BALB/c nude mice." (PMID 37378658, 2023). "In summary, our study unveils a new intracellular metabolic pathway of 5hmdC and 5fdC reliant on DCK and DCTD, which mediates the anti-tumor effects and expands the therapeutic potential of these compounds." (PMID 37378658, 2023). "Abnormal expression of DCTD would affect the stability of genetic material synthesis, which is vital important for rapid tumor expansion." (PMID 28912488, 2017). "Xenograft tumor growth of wild-type Raji cells was significantly restricted by 5hmdC treatment while that of DCTD-deficient cells was not affected." (PMID 37378658, 2023). "As the abundance of DCK determines the tumor killing effect of oxidized methylcytidines in a DCTD-dependent manner, expression analysis of components of the DCK-DCTD axis in patients would provide a useful biomarker in cancer therapeutic applications of 5hmdC and 5fdC." (PMID 37378658, 2023). "DCTD was strongly expressed in both tumor cells and stromal cells." (PMID 33287390, 2020). "The pharmacokinetics of gemcitabine in tumor cells is regulated by human equilibrative nucleoside transporters (hENTs)-mediated uptake, activation by deoxycytidine kinase (DCK), and inactivation by cytidine deaminase (CDA), deoxycytidylate deaminase (DCTD), and cytosolic 5′-nucleotidases (NT5C1A)." (PMID 33546284, 2021).
cancer (5 papers, 2017 to 2023). A tumor composed of atypical neoplastic, often pleomorphic cells that invade other tissues. "Its use was tested for the estimation of the role of CDD and dCMP deaminase in five cancer and four non-cancer cell lines." (PMID 37993628, 2023). "Expression analysis of the key enzymes that regulate gemcitabine uptake (hENT1) and intracellular metabolism (CDA, DCK, NT5C1A, and DCTD) was performed in cancer cells and PSCs by immunofluorescence and by western blot analysis using total cell lysates." (PMID 33287390, 2020). "DCTD is a key enzyme in genetic material synthesis, taking charge of conversion of dCMP to dUMP, which is necessary in cancer origin and progression." (PMID 28912488, 2017). "We speculate that DCTD acts as a “biosynthetic catalyst” in cancer progression to meet the rapid cell proliferation and active demand for genetic material." (PMID 28912488, 2017). "Certain cancer cells rely on the salvage enzymes cytidine deaminase (CDA) and dCMP deaminase (DCTD) to inactivate these cytidine derivative drugs by deamination." (PMID 37378658, 2023). "The data showed that in contrast to the cancer cells, all the non-cancer cells used in the study exhibited low, if any, CDD content and their cytidine deaminase activity can be exclusively attributed to dCMP deaminase." (PMID 37993628, 2023). "The only exception was the 143B TK cell line, where a much higher ability to produce EdU signal in DNA was observed than in the non-cancer cell lines, although 143B TK cells expressed dCMP deaminase similarly to the non-cancer cells." (PMID 37993628, 2023). "In human cancer cells, 5hmdCMP and 5fdCMP can be generated by DCK through the phosphorylation of 5hmdC and 5fdC, thus providing potential substrates for DCTD." (PMID 37378658, 2023).
infection (3 papers, 2015 to 2024). The state of being infected such as from the introduction of a foreign agent such as serum, vaccine, antigenic substance or organism. "In total, 2.5 × 108 WT HAP1, DCTD KO and TOPORS KO HAP1 cells were infected with the pre-packaged genome-wide All-in-One Brunello lentiviral library (Addgene 73179) at a multiplicity of infection (MOI) of 0.2." (PMID 38760575, 2024).
DCTD also shares sentences with these, for which no sentence is quoted: diabetes (1 paper); Hepatomas (1).